TRAFD1 (TRAF-type zinc finger domain containing 1)
Description:
Negative feedback regulator that controls excessive innate immune responses. Regulates both Toll-like receptor 4 (TLR4) and DDX58/RIG1-like helicases (RLH) pathways. May inhibit the LTR pathway by direct interaction with TRAF6 and attenuation of NF-kappa-B activation. May negatively regulate the RLH pathway downstream from MAVS and upstream of NF-kappa-B and IRF3 (By similarity).
Synonyms: FLN29
Tractability: PROTAC: ubiquitination databases record sites on it; its protein half-life has been measured.
Gene: Protein-coding gene on chromosome 12 (112,125,514 to 112,153,610, forward strand). Ensembl gene ENSG00000135148.
Subcellular location (Human Protein Atlas): Nucleoplasm; Actin filaments; Cytosol; Focal adhesion sites
Gene Ontology:
Molecular function: protein binding
Biological process: negative regulation of innate immune response
Cellular component: mitochondrion
Genetic constraint (gnomAD): Loss-of-function variants: 37 observed, 65.02 expected, observed/expected ratio (o/e) 0.57, 90% interval 0.44 to 0.75. The upper end of that interval is the gene's LOEUF score, 0.75, which puts it in group 3 of 6, group 1 being the genes least tolerant of losing a copy. Missense variants: 617 observed, 733.99 expected, observed/expected ratio (o/e) 0.84, 90% interval 0.79 to 0.9. Synonymous variants: 221 observed, 267.02 expected, observed/expected ratio (o/e) 0.83, 90% interval 0.74 to 0.93.
Homologues: Orthologues: chimpanzee TRAFD1 (98% identical), macaque TRAFD1 (96% identical), dog TRAFD1 (84% identical), pig TRAFD1 (80% identical), rabbit TRAFD1 (80% identical), mouse Trafd1 (76% identical), rat Trafd1 (76% identical), guinea pig TRAFD1 (75% identical), zebrafish trafd1 (32% identical), tropical clawed frog trafd1 (31% identical). Paralogues in human: XAF1 (14% identical).
Diseases named in the same sentence as TRAFD1 in open-access papers:
TRAFD1 is named in the same sentence as 22 diseases in open-access papers, as found by Europe PMC text mining. Sharing a sentence is not in itself a finding about the gene and the disease. The quoted sentences say what the papers report.
celiac disease (3 papers, 2020 to 2025). An autoimmune genetic disorder with an unknown pattern of inheritance that primarily affects the digestive tract. "In celiac disease, TRAFD1 was recognized as an upstream regulator of IFNg signaling and thereby activating cytotoxic T-cells, an important pathomechanism." (PMID 39794498, 2025). "We present data regarding the expression of HLA-DQ2.5 and TRAFD1 genes in celiac disease patients on active disease or remission." (PMID 38694231, 2024). "In conclusion, TRAFD1/FLN29 may represent a direct biomarker of celiac disease remission and compliance with a gluten-free diet in treated patients." (PMID 38694231, 2024). "More recently, TRAFD1 has been associated with celiac disease and defined as a novel master regulator, involved in the regulation of a set of genes enriched for two major pathways of immune activation, IFNγ signalling and antigen processing/presentation." (PMID 38694231, 2024). "The TRAFD1 gene is an important mediator of the inflammatory process and could be a useful biomarker of celiac disease remission and compliance with a gluten-free regimen in treated patients." (PMID 38694231, 2024).
influenza (3 papers, 2014 to 2024). An acute viral infection of the respiratory tract, occurring in isolated cases, in epidemics, or in pandemics; it is caused by serologically different strains of viruses (influenzaviruses) designated A, B, and C, has a 3-day incubation period, and usually lasts for 3 to 10 days. "TRAFD1 is a negative regulator of toll-like receptor signaling which is upregulated in influenza-infected hNECs." (PMID 31461941, 2019). "In addition, we found that several biomarkers, Cxcl9, Trafd1, and C2 were candidates for evaluating differences between alum-adjuvanted influenza vaccines and nonadjuvanted vaccines." (PMID 25010690, 2014).
colitis (1 paper, 2023). Inflammation of the colon. "We observed several upregulated genes associated with colitis and IBD development, including ABCA2, Acss1, Araf, CSAD, Ilf3, and TRAFD1, showing similar fold change patterns across treatment groups." (PMID 37909786, 2023).
lung adenocarcinoma (1 paper, 2022). A carcinoma that arises from the lung and is characterized by the presence of malignant glandular epithelial cells. "In lung adenocarcinoma (LUAD), IFN-γ response genes, TRAFD1 is reported to exhibit significant expression and a strong positive correlation with OAS3." (PMID 36672782, 2022).
melanoma (1 paper, 2018). A malignant, usually aggressive tumor composed of atypical, neoplastic melanocytes. "On SSC14, a synonymous coding SNP in the TRAFD1 (TRAF-Type Zinc Finger Domain Containing 1) gene reached a p-value of 1.91 × 10–5, although no direct link exists between melanoma occurrence and TRAFD1 function, a regulator of toll-like receptor signaling." (PMID 29963229, 2018).
osteoarthritis (1 paper, 2018). A noninflammatory degenerative joint disease occurring chiefly in older persons, characterized by degeneration of the articular cartilage, hypertrophy of bone at the margins and changes in the synovial membrane. "Furthermore, TRAFD1 is suggested to induce inflammatory expression of MMP13 in osteoarthritis." (PMID 29931419, 2018).
Osteochondrosis (1 paper, 2018). Abnormal growth ossification centers in children. "Moreover, the TRAFD1 gene is also located in a QTL for osteochondrosis score in a Duroc × Pietrain resource population, indicating an involvement in bone metabolism." (PMID 29931419, 2018).
renal carcinoma (1 paper, 2019). A carcinoma arising from the epithelium of the renal parenchyma or the renal pelvis. "Finally, TRAFD1 is found to have a very low difference in expression compared to the control group in colon,ovarian, brain and renal cancer types." (PMID 31831960, 2019).
cancer (4 papers, 2019 to 2023). A tumor composed of atypical neoplastic, often pleomorphic cells that invade other tissues. "Genes that have a very similar expression pattern to the control group and appear as such in 4 out of six cancer types are PATE, NEUROD4 and TRAFD1." (PMID 31831960, 2019). "Genes having similar expression (referred as flexible genes) pattern to thecontrol group in four out of six cancer types are PATE, NEUROD4 and TRAFD1." (PMID 31831960, 2019). "The follow-up research showed that TRPV4 might affect the generation of cancer by influencing gene expression or function of SH3RF3, CHFR, ZTB1, and TRAFD1." (PMID 35813831, 2022). "In addition, the survival analysis emphasized the prognostic significance of TRAFD1, SOD2, RIPK2, RBCK1, and MT2A as cancer-promoting factors in ccRCC and pRCC." (PMID 34795663, 2021).
bone disorder (1 paper, 2018). "The nominal significant association with serum P levels and literature evidence for its contribution to bone disorders emphasize TRAFD1 as a promising candidate gene for further analyses regarding the connection between P homeostasis and immune system." (PMID 29931419, 2018).
infection (1 paper, 2023). The state of being infected such as from the introduction of a foreign agent such as serum, vaccine, antigenic substance or organism. "TRAFD1 upregulation suggests a host attempt to slow immune response common during pathogen infection response." (PMID 37909786, 2023).
TRAFD1 also shares sentences with these, for which no sentence is quoted: colon cancer (1 paper); Crohn disease (1); gout (1); hepatitis E virus infection (1); Hypertension (1); intestinal cancer (1); ischemic heart disease (1); retinal degeneration (1); Stroke (1); tumor (1); type 2 diabetes (1).